GAS7 (growth arrest specific 7)
Description:
May play a role in promoting maturation and morphological differentiation of cerebellar neurons.
Synonyms: KIAA0394; MGC1348
Tractability: Antibody: its Gene Ontology location is reachable by antibodies, with medium confidence; the Human Protein Atlas places it where antibodies can reach. PROTAC: ubiquitination databases record sites on it; its protein half-life has been measured.
Gene: Protein-coding gene on chromosome 17 (9,910,606 to 10,198,853, reverse strand). Ensembl gene ENSG00000007237.
Subcellular location: Cytoplasm
Subcellular location (Human Protein Atlas): Plasma membrane; Actin filaments; Focal adhesion sites
Gene Ontology:
Molecular function: protein binding
Biological process: clathrin coat assembly; clathrin-dependent endocytosis; neuron projection morphogenesis
Cellular component: clathrin-coated pit; clathrin-coated vesicle; cytoplasm; plasma membrane
Genetic constraint (gnomAD): Loss-of-function variants: 20 observed, 43.14 expected, observed/expected ratio (o/e) 0.46, 90% interval 0.32 to 0.67. The upper end of that interval is the gene's LOEUF score, 0.67, which puts it in group 2 of 6, group 1 being the genes least tolerant of losing a copy. Missense variants: 289 observed, 425.6 expected, observed/expected ratio (o/e) 0.68, 90% interval 0.62 to 0.75. Synonymous variants: 173 observed, 171.51 expected, observed/expected ratio (o/e) 1.01, 90% interval 0.89 to 1.14.
Cancer hallmarks: invasion and metastasis (suppresses)
Homologues: Orthologues: chimpanzee GAS7 (100% identical), mouse Gas7 (97% identical), pig GAS7 (97% identical), rat Gas7 (97% identical), rabbit GAS7 (87% identical), guinea pig GAS7 (86% identical), dog GAS7 (78% identical), tropical clawed frog gas7 (72% identical), macaque GAS7 (63% identical), zebrafish gas7a (55% identical). Paralogues in human: PSTPIP1 (16% identical), FCHO1 (14% identical), FCHO2 (13% identical), PSTPIP2 (13% identical), SGIP1 (6% identical).
Diseases named in the same sentence as GAS7 in open-access papers:
GAS7 is named in the same sentence as 55 diseases in open-access papers, as found by Europe PMC text mining. Sharing a sentence is not in itself a finding about the gene and the disease. The quoted sentences say what the papers report.
lung carcinoma (10 papers, 2015 to 2023). "On a cellular level, it is shown that miR-181a-5p is associated with gefitinib resistance in the PC9GR lung cancer cell line through direct targeting of GAS7, which is involved in the regulation of AKT/ERK pathways." (PMID 37697308, 2023). "A low level of GAS7 mRNA expression is associated with a poorer survival among these patients with late-stage lung cancer from the TCGA database (p = 0.026)." (PMID 26506240, 2015). "This loss of heterozygosity has been found to be associated with a decrease in GAS7 transcription in lung cancer patients, indicating a potential role for GAS7 as a tumor suppressor in lung cancer." (PMID 26506240, 2015). "Cancer fusion gene GAS7 is located at this locus, which suppresses tumor cell migration in lung cancer." (PMID 32619008, 2020). "For example, Moonlight identified GAS7 as a hypermethylated tumor suppressor in lung cancer and as an hypomethylated oncogene in head-and-neck squamous cell tumors." (PMID 31900418, 2020). "Some genes with hypermethylated promoters have been reported in lung cancer, such as GAS7, AQP10, HLF, and HOPX." (PMID 30867848, 2019). "In a study related to nonsmall-cell lung cancer, it has been reported that the high level of mRNA of growth arrest-specific 7 (GAS7) is related to the improvement of overall survival, and downregulation of its expression can antagonize the resensitivity of gefitinib in lung cancer cells." (PMID 35942407, 2022). "Furthermore, several epigenomic analyses revealed the hypermethylation pattern of GAS7 in lung cancer, prostate cancer, CRC, and pancreatic endocrine tumors (PETs)." (PMID 32605309, 2020). "miR‐181a is related to Gefitinib resistance in lung cancer through an increased expression profile compared with the sensitive models and direct targeting of GAS7; GAS7 is involved in the regulation of AKT/ERK pathways and EMT markers and is downregulated in plasma from Gefitinib‐resistant patients." (PMID 30548184, 2019). "Previous studies showed that chromosome deletion and promoter methylation could be the reasons for lower GAS7 expression in lung cancer." (PMID 29706651, 2018). "To examine the protein expression of GAS7 isoforms in the lung cell model, we performed Western blot analysis of protein extracts from two human normal lung cell lines (Beas2B and MRC5) and six lung cancer cell lines (A549, H226, H226Br, CL1-0, CL1-5, and H460)." (PMID 26506240, 2015). "We additionally identified statistically significant mutations in the metalloproteinases ADAMTS2 (15%) and ADAMTS12 (20%), and in GAS7 (12%) and NTM (10%) (Q < 0.01, Methods section), which so far have not been reported as significantly mutated in any other lung cancer subtype." (PMID 29535388, 2018).
breast carcinoma (9 papers, 2014 to 2024). "In breast cancer, GAS7 was associated with CYFIP1 and WAVE2 complex to suppress breast cancer metastasis via blocking CYFIP1 and Rac1 protein interaction, actin polymerization, and β1-integrin/FAK/Src signaling." (PMID 38370374, 2024). "Our analysis of clinical samples and public data reveal an association of lower GAS7 expression with breast cancer metastasis and poor survival." (PMID 29706651, 2018). "Moreover, the Schmidt breast cancer data set (GEO accession: GSE11121) showed that the trend of lower GAS7 expression was associated with overall metastatic events, as well as metastasis within 5 years." (PMID 29706651, 2018). "Downregulation of GAS7 has been reported in several cancer types, and ectopic expression of GAS7 inhibited the migration of lung and breast cancer cells." (PMID 34201353, 2021). "We examined the GAS7 expression in the breast cancer patients from Curtis breast data set, from which 1972 patients with 10-year survival record were selected." (PMID 29706651, 2018). "Overall, these results suggest that GAS7 associates with CYFIP1 to perturb the binding of CYFIP1 and active form of Rac1, thus resulting in the inhibition of actin polymerization in breast cancer cells." (PMID 29706651, 2018). "The GAS7 gene showed significantly lower expression in the early onset breast cancer patients (≤40 years old) than in elder patients." (PMID 29706651, 2018). "The analysis from data sets indicates that lower GAS7 expression level is correlated with breast cancer metastasis." (PMID 29706651, 2018). "To identify the potential upstream regulator for GAS7 gene expression in breast cancer cells, we applied PROMO website to predict possible transcription factors of GAS7." (PMID 29706651, 2018). "We found that GAS7 was associated with CYFIP1 and WAVE2 complex to suppress breast cancer metastasis via blocking CYFIP1 and Rac1 protein interaction, actin polymerization, and β1-integrin/FAK/Src signaling." (PMID 29706651, 2018). "Furthermore, the analysis from Bild breast data set (GEO accession: GSE3143) showed that the breast cancer patients having higher GAS7 expression displayed better 5 years survival after initial diagnosis than the lower GAS7 expression patients." (PMID 29706651, 2018). "Overall, our study suggests that GAS7 could be a useful biomarker for early onset, as well as for metastasis and survival of breast cancer." (PMID 29706651, 2018).
breast carcinoma (continued). "In this study, we found that lower GAS7 expression significantly correlated with not only the early onset breast cancer, but also with tumor metastasis and patient survival, suggesting GAS7 may play a role in tumorigenicity and aggressiveness in early onset breast cancer." (PMID 29706651, 2018). "Therefore, we decided to further investigate the role of GAS7 in early onset breast cancer." (PMID 29706651, 2018). "For example, in CD4+ T-cells, BCL9 for B-cell acute lymphoblastic leukemia (B-ALL); GAS7 and PRDM16 for Acute myelogenous leukemia (AML); ESR1 for breast cancer; and GRIN2A for colorectal, lung, and gastric carcinoma were differentially methylated between PWH and PWoH." (PMID 38466776, 2024).
glaucoma (9 papers, 2012 to 2024). Increased pressure in the eyeball due to obstruction of the outflow of aqueous humor. "Strong associations with IOPg, IOPcc and glaucoma for the GAS7 variant for example suggest that its effect on CRF is via IOP." (PMID 33311554, 2020). "GAS7 may interact with other genes implicated in glaucoma pathogenesis such as MYOC, OPTN, WDR36, CAV1, nitric oxide synthase 2 (NOS2), forkhead box C1 (FOXC1), apolipoprotein E (APOE), amyloid precursor protein (APP), and clusterin (CLU)." (PMID 32545285, 2020). "Growth arrest-specific 7 (GAS7), one of the genes that influence IOP, is found in a chromosomal area previously identified by a glaucoma linkage study and subsequently by a genome-wide association study (GWAS)." (PMID 35411287, 2022). "We identified common variants in GAS7 and TMCO1 that altered the susceptibility to both IOP and glaucoma." (PMID 22570627, 2012). "We investigated the associations of the GAS7 rs11656696 minor allele (A) and the TMCO1 rs7555523 minor allele (C) with glaucoma in 4 case-control studies from the Netherlands and Germany." (PMID 22570627, 2012). "GAS7 and TMCO1 are expressed in ocular cells and tissues implicated in glaucoma." (PMID 22570627, 2012). "GAS7 is located in a chromosomal region previously identified by a linkage study of glaucoma." (PMID 22570627, 2012). "Finally, GAS7 is regulated by transforming growth factor (TGF) beta, which has previously been implicated in trabecular outflow as well as in the development of the optic disc (the primary site of neuronal damage by glaucoma)." (PMID 22570627, 2012). "Regarding the genetic aspect, SNPs with high OR values for glaucoma exposure on cataract were TMCO1-AS1 (rs2814471 with OR = 1.370), GAS7 (rs12602519 with OR = 1.178), ABCA1;SLC44A1 (rs2472493 with OR = 1.162), and GNB1L;TXNRD2 (rs58714937 with OR = 1.153)." (PMID 38674349, 2024). "The finding of reduced peripapillary RFNL thickness in patients with the SIX6 risk variant, but not in those with the GAS7 variant, implies that the pathologic changes in glaucoma associated with the SIX6 variant may occur primarily in the RGCs and their axons." (PMID 29261660, 2017). "GAS7 and TMCO1 are expressed in the ocular tissues that are involved in glaucoma." (PMID 22570627, 2012). "High GAS7 expression has previously been shown in amacrine cells in the mouse retina, while lower expression was found in retinal cell types which are usually not affected by glaucoma." (PMID 22570627, 2012). "Moreover, high expression of GAS7 has been demonstrated in amacrine cells in the mouse retina, whereas lower expression GAS7 has been demonstrated in retinal cell types, which are usually not affected by glaucoma." (PMID 32545285, 2020).
acute myeloid leukemia (5 papers, 2013 to 2024). Acute myeloid leukemia (AML) is a group of neoplasms arising from precursor cells committed to the myeloid cell-line differentiation. "Controlled expression of Gas7 also appears to be critical for tissue development since MLL-GAS7 translocations were detected in individuals suffering of treatment-related acute myeloid leukemia." (PMID 23840221, 2013). "A previous study indicated the tumour suppressive effect of GAS7 on acute myeloid leukaemia." (PMID 36908025, 2023).
neuroblastoma (5 papers, 2004 to 2023). Neuroblastoma (NB) is the most common solid, extracranial childhood tumor. "More recently, it was reported that loss of GAS7 expression accelerated metastasis of neuroblastoma harboring MYCN overexpression or amplification." (PMID 34201353, 2021). "Thus, loss of GAS7 is one of the main events driving metastasis in neuroblastoma." (PMID 37274289, 2023). "Dong and colleagues have reported the first genetic evidence linking GAS7 deficiency and metastasis in MYCN-driven neuroblastoma." (PMID 37274289, 2023). "Next, using both zebrafish and mammalian model systems, they show that reduced expression of the GAS7 promotes metastasis of MYCN-amplified neuroblastoma cells." (PMID 37274289, 2023). "GAS7 depletion resulted in enhanced metastatic capacity of neuroblastoma." (PMID 36908025, 2023). "Repression of GAS7 resulted in enhanced metastatic potential of neuroblastoma." (PMID 36908025, 2023). "Also, GAS-7 is involved in controlling growth arrest and apoptosis of neuroblastoma cells in response to various stimuli." (PMID 30713602, 2019).
schizophrenia (5 papers, 2016 to 2024). A major psychotic disorder characterized by abnormalities in the perception or expression of reality. "In the same covariate analyses, when considering trend-significant associations, we identified genes such as TRIM10 and GAS7, associated with schizophrenia, MACROH2A1, related to autism-like behaviors, and ADORA2A, associated with anxiety disorders." (PMID 39020437, 2024). "Our results identify GAS7 as a susceptibility gene for schizophrenia and highlight the functional importance of proteins directly regulating membrane deformation for proper neuronal migration and morphogenesis." (PMID 27189492, 2016). "In our research, we identified growth arrest specific gene 7 (GAS7) as a schizophrenia risk gene in two independent Han Chinese populations using a two-stage association study." (PMID 27189492, 2016). "Additionally, GAS7 is associated with schizophrenia and plays a role in regulating neuronal migration and morphogenesis." (PMID 37664546, 2023). "We found that GAS7 is significantly associated with schizophrenia." (PMID 27189492, 2016). "The impaired pre-pulse inhibition (PPI) of Gas7-deficient mice might mirror the disease-related behavior in schizophrenia." (PMID 27189492, 2016). "Our results revealed that GAS7 is significantly associated with schizophrenia." (PMID 27189492, 2016). "Our results demonstrate GAS7 as a susceptibility gene for schizophrenia." (PMID 27189492, 2016). "So, together with our genetic and functional study, the deficit in PPI could suggest that GAS7 might be a risk gene for schizophrenia." (PMID 27189492, 2016). "In addition, Gas7-deficient mice showed sensorimotor gating deficits, which could be a manifestation of schizophrenia-related behaviors." (PMID 27189492, 2016). "Considering that both actin and microtubules are essential in neural development and schizophrenia has been long considered a neurodevelopmental disease, we hypothesized that GAS7 might be a susceptibility gene of schizophrenia and conducted a two-stage association study." (PMID 27189492, 2016). "GAS7, at chromosome 17p31.1, is quite close to a cannabis receptor associated with IOP at chromosome 17p31.3, and has been linked with schizophrenia in a Chinese population." (PMID 39482785, 2024). "In light of these findings, we hypothesized that Gas7 might play a role in the pathogenesis of schizophrenia and deficits in Gas7 might impact normal brain development." (PMID 27189492, 2016). "Further investigation of the roles of Gas7 in the pathogenesis of schizophrenia is warranted." (PMID 27189492, 2016). "Gas7 might participate in the pathogenesis of schizophrenia by regulating neurite outgrowth and neuronal migration through its C-terminal F-BAR domain." (PMID 27189492, 2016). "Our results suggest that GAS7 is a candidate gene for schizophrenia." (PMID 27189492, 2016). "Considering all the effects observed above, we wondered whether changes in Gas7 expression level would induce schizophrenia-like behaviors." (PMID 27189492, 2016). "Previous research demonstrated that Gas7 is highly expressed in cerebral cortex, hippocampus and cerebellum, all of which are reported to be key brain regions involved in the pathogenesis of schizophrenia." (PMID 27189492, 2016).
ovarian carcinoma (4 papers, 2021 to 2025). A malignant neoplasm originating from the surface ovarian epithelium. "Circ_0078607 enhanced cisplatin sensitivity in ovarian cancer cells by regulation of miR-196b-5p and GAS7 (growth arrest-specific 7) expressions." (PMID 38152652, 2023).
melanoma (3 papers, 2020 to 2024). A malignant, usually aggressive tumor composed of atypical, neoplastic melanocytes. "Decreased expression of GAS7 gene in melanoma cells can be attributed to increased expression of genes involved in methylation (DNMT3B)." (PMID 34914337, 2021). "In conclusion, it seems that our predicted miRNAs have a regulatory role on DNMT3B and GAS7 genes and alteration of their expression can be considered as a new therapeutic approach (alone or in combination with other methods) for melanoma." (PMID 34914337, 2021). "Accordingly, in the present study we aimed to predict regulatory effect of miRNAs on DNMT3B and GAS7 genes expression in melanoma cell line." (PMID 34914337, 2021). "To investigate the possible indirect effect of miRNAs on expression of DNMT3B and GAS7 genes, we quantified the expression of these genes in melanoma cells and normal melanocytes." (PMID 34914337, 2021). "As an alternative, in this study, we used bioinformatics prediction to find miRNAs that are involved in the regulation of DNMT3B and GAS7 genes of melanoma cells and melanocytes." (PMID 34914337, 2021). "Compared to control, the expression of GAS7 gene in melanoma cells showed a significant decrease (p value = 0.0323)." (PMID 34914337, 2021). "The results demonstrated that the DNMT3B and GAS7 genes were significantly up- and down-regulated in melanoma cells compared to melanocytes, respectively." (PMID 34914337, 2021). "Therefore, in the present study, we aimed to predict microRNAs involved in DNMT3B gene methylation through bioinformatics approaches and examined their effect on DNMT3B and GAS7 genes expression in melanoma cells." (PMID 34914337, 2021). "Furthermore, results of GEPIA analysis showed that ACTB, SLC1A5, VASP, BRBB3, GAS7, ARTN2, and SOX5 were significantly increased in melanoma tissues (p < 0.05)." (PMID 38561355, 2024).
acute lymphoblastic leukemia (2 papers, 2020 to 2024). Leukemia with an acute onset, characterized by the presence of lymphoblasts in the bone marrow and the peripheral blood. "On the contrary, GAS7 has a pro-proliferative role in pre-B acute lymphoblastic leukemia cells, possibly through regulating Stat5, AKT, and Erk proliferation signals." (PMID 31925702, 2020).
Alzheimer disease (2 papers, 2025). A progressive, neurodegenerative disease characterized by loss of function and death of nerve cells in several areas of the brain leading to loss of cognitive function such as memory and language. "GAS7 has also been implicated in SCZ and Alzheimer’s disease (AD)." (PMID 40799747, 2025).